Y_RNA (Y RNA )
Gene: Miscellaneous RNA gene on chromosome 16 (14,275,508 to 14,275,600, forward strand). Ensembl gene ENSG00000201075.
Homologues: Orthologues: chimpanzee Y_RNA (97% identical). Paralogues in human: RNY3P1 (89% identical), Y_RNA (89% identical), Y_RNA (88% identical), RNY3 (87% identical), Y_RNA (87% identical), RNY3P11 (86% identical), Y_RNA (86% identical), RNY3P10 (85% identical), Y_RNA (85% identical), RNY3P14 (84% identical), Y_RNA (84% identical), RNY3P7 (83% identical), and 92 more.